LYZ (lysozyme)
Diseases named in the same sentence as LYZ in open-access papers (continued):
Sharing a sentence is not in itself a finding about the gene and the disease.
enteritis (7 papers, 2021 to 2025). Inflammation of the small intestine. "In broilers challenged with Eimeria maxima and C. perfringens, adverse health effects from necrotic enteritis were reduced by feeding on diets containing lysozyme-based antimicrobial blends." (PMID 37106919, 2023). "In this study, insect meal was effective in preventing enteritis by lowering the expression of prostaglandin and interferon regulatory factor 1 in the gut, while the highest inclusion level also improved serum lysozyme activity." (PMID 35565636, 2022). "Typical enteritis features and fluctuations of immune system occur, which can be observed in the enzyme activities of total superoxide dismutase and lysozyme and in the contents of immunoglobulin M, complement 3 and complement." (PMID 36601073, 2022). "Typical enteritis characteristics and immune fluctuations appeared, as reflected by the enzyme activities of total superoxide dismutase and lysozyme, and the contents of immunoglobulin M, complement 3, and complement." (PMID 35296073, 2022). "The use of lysozyme has already demonstrated benefits in reducing necrotic enteritis." (PMID 41514707, 2025). "In this study, dietary FSBM significantly affected the intestinal flora of the pearl gentian grouper, which was confirmed by the significant variations in lysozyme, indicating that the intestinal flora may play an important role in the process of FSBM-induced enteritis." (PMID 33967821, 2021).
Parkinson disease (7 papers, 2015 to 2025). A progressive degenerative disorder of the central nervous system characterized by loss of dopamine producing neurons in the substantia nigra and the presence of Lewy bodies in the substantia nigra and locus coeruleus. "There are several diseases associated with amyloid aggregates, such as Alzheimer’s, Parkinson’s, lysozyme amyloidosis, and others." (PMID 37836734, 2023).
histiocytic sarcoma (6 papers, 2012 to 2022). An aggressive malignant neoplasm with a poor response to therapy, usually presenting as stage III/IV disease. "The expression of at least two of the following markers-CD 68, CD 163, CD 4, and lysozyme-has been suggested as a diagnostic criterion for histiocytic sarcoma." (PMID 36721560, 2022). "Several male mice also had eosinophilic (hyaline) protein droplets in the renal tubules consistent with lysozyme accumulation associated with histiocytic sarcoma." (PMID 27549339, 2016). "At least two of the markers cluster of differentiation (CD) 68, CD 163, CD 4, and lysozyme have to be positive on immunohistochemistry to diagnose histiocytic sarcoma." (PMID 36721560, 2022). "In addition, in a model of histiocytic sarcoma, neoplastic histiocytes produced lysozyme, and lysozyme accumulated in tubular epithelial cells." (PMID 34205864, 2021). "In immunohistochemistry, these atypical cells were specifically positive for CD68 (KP-1), CD163, and lysozyme, which was consistent with histiocytic sarcoma (HS) of the spleen." (PMID 23075171, 2012). "Previously, immunohistochemical markers used for histiocytic sarcomas in rats included vimentin, CD68 and lysozyme." (PMID 35454212, 2022). "Histiocytic sarcoma (HS) is an uncommon malignant neoplasm arising from mature histiocytes and most commonly characterized by the immunophenotypic expression of CD68, CD163, or lysozyme." (PMID 31687231, 2019).
immune deficiency (6 papers, 2019 to 2025). "The levels of lysozyme, interleukin (IL)-2, IL-10, and IgA in blood serum at this age were minimal; starting from 28 days of age, there is a specific humoral immune deficiency, which is compensated by strengthening of cellular defense factors." (PMID 38911092, 2024). "The crustin a (cru a), immune deficiency (imd), and lysozyme (lzm) mRNA levels were significantly higher in the R10, R20, and R40 groups than in the other groups (p < 0.05)." (PMID 36552499, 2022). "Ascorbic acid can enhance lysozyme damage caused by immune deficiency." (PMID 38895183, 2024). "This was evident in L. vannamei, which exhibited increased expression of immune-related genes, specifically toll-like receptor messenger ribonucleic acid (mRNA), immune deficiency (IMD) mRNA, and lysozyme (LZM) mRNA, with a 4% SL inclusion level." (PMID 40547201, 2025). "These defenses include encapsulation, phagocytosis, melanization, increased lysozyme activity, prophenoloxidase activation cascade, and production of antimicrobial peptides regulated by the IMD (immune deficiency) and Toll signaling pathways, among others." (PMID 39511654, 2024).
immunotoxicity (6 papers, 2020 to 2024). "Herbicides toxicity induces immunotoxicity through a complex network of inflammatory cytokines release, immunoglobulins regulation, immune cell proliferation inhibition, and lysozyme activity changes." (PMID 35773603, 2023). "Five genes (CD8A, CYP1A1, ITGAX, LYZ, and PTPRC) associated with immunotoxicity were among the most up‐regulated genes exposed to dose 1:8 indoor PM." (PMID 31883508, 2020). "Additional long-term biomonitoring, toxicokinetic, and immune-health studies are needed to elucidate the factors influencing the impacts of PFAS exposure on lysozyme activity, it is clear that changes in lysozyme activity alone are insufficient as a biomarker of PFAS-related immunotoxicity." (PMID 36337916, 2022).
oral diseases (6 papers, 2013 to 2024). "sIgA, along with various antimicrobials (such as lysozyme, lactoferrin, salivary peroxidase, and visfatin), limits microbial adhesion to epithelial and tooth surfaces, thereby helping to prevent oral diseases." (PMID 39152368, 2024). "Salivary components such as lysozyme, histatins and lactoferrin provide an antimicrobial function crucial to prevent progression of oral diseases." (PMID 23437114, 2013). "Based on the limited literature available, the primary aim of this pilot study was to evaluate salivary pH and certain salivary analytes relevant to oral health, such as amylase, lactate dehydrogenase (LDH), lysozyme, calcium (Ca), and phosphorus (P) in healthy adult dogs with no oral disease." (PMID 29126424, 2017).
C. perfringens infection (5 papers, 2018 to 2024). "In chickens, exogenous lysozyme supplementation inhibits the overgrowth of Escherichia coli and Lactobacillus and reduces the intestinal lesion scores after Clostridium perfringens infection." (PMID 37582766, 2023). "Exogenous lysozyme supplementation may enhance intestinal immunity to directly resist Clostridium perfringens infection in chickens, which reduces the dependence on Lactobacillus to resist Clostridium perfringens infection." (PMID 37582766, 2023). "In the current study, NE infection significantly downregulated LYZ and fowlicidin-2 gene expression, implying that birds were more prone to C. perfringens infection, as evidenced by the higher level of C. perfringens that was detected in the gut and liver of NE-infected birds." (PMID 29416856, 2018).
glioma (5 papers, 2018 to 2025). A benign or malignant brain and spinal cord tumor that arises from glial cells (astrocytes, oligodendrocytes, ependymal cells). "A recombinant lysozyme poliovirus PVSRIPO that activates antitumor immune response has improved OS in glioma patients in a trial." (PMID 36065303, 2022). "This suggests that the impact of LYZ on immune cell polarization and function may vary across different glioma subtypes, potentially influencing their prognosis and treatment response." (PMID 41514850, 2025). "LYZ is marked as the aging-related gene which is controlled by NLRP3 in glioma progression." (PMID 33193654, 2020). "PLVAP-targeted ferritin nanocarriers and lysozyme-dextran nanogel nanocarriers have been demonstrated to provide effective and precise targeting, as ferritin nanocarriers can easily pass through the BBB while loading glioma-targeted drugs." (PMID 36033326, 2022).
hepatocellular carcinoma (5 papers, 2021 to 2025). A malignant tumor that arises from hepatocytes. "And LYZ is considered a potential biomarker and target for hepatocellular carcinoma." (PMID 39555091, 2024). "Increased abundance of ARRB1, as well as FBXO11, LYZ, RPS6KB1, and SYNGR2 have comparable oncogenic effects in hepatocellular carcinoma, and MGST1 and RPS6KB1 have noted oncogenic roles in various lung cancers." (PMID 40186098, 2025). "Moreover, hepatocellular carcinoma (HCC) cells were also found to express and secrete LYZ, which appears to be regulated by cytokine-mediated signaling and Wingless-related integration site (WNT) signaling activation." (PMID 40046560, 2025).
lung carcinoma (5 papers, 2017 to 2025). "Oral lysozyme can also reduce the metastasis of Lewis in mouse lung carcinoma, improving the efficacy of 5-FU on primary tumor growth and lung metastasis." (PMID 34925025, 2021). "There might be a crucial function for SDF-1/CXCR4 in promoting chemotaxis lung cancer cells gather to the brain astrocytes and secreting lysozyme to damage BBB." (PMID 34531745, 2021). "Based on Cui huaibo’s finding, lysozyme was related to the invasion of lung cancer cells." (PMID 34925025, 2021). "In this study, we postulated that FA-ExoPAC releases PAC inside the cancer cells either through direct release or by the lysozyme-mediated digestion, which was clearly demonstrated by its in vivo antitumor response against subcutaneous and orthotropic lung cancer xenografts." (PMID 34359601, 2021). "The study found that lysozyme mediated the invasion and migration of A549 cells by activating Rho family proteins of related cytoskeleton signaling pathways, which suggests that lysozyme may be a potential protein marker for the progression and prognosis of lung cancer." (PMID 34925025, 2021).
lymphoma (5 papers, 2011 to 2025). A malignant (clonal) proliferation of B- lymphocytes or T- lymphocytes which involves the lymph nodes, bone marrow and/or extranodal sites. "Overall, it should be noted that serum ACE, lysozyme and sIl-2R may also be elevated due to other diseases, such as malignant lymphoma or infections." (PMID 35011651, 2021). "Furthermore, our study identifies CIITA, LYZ, MBL2, and CD40 as potential therapeutic targets for various types of lymphoma treatment." (PMID 40360443, 2025). "The lymphoma cells were positive for CD3 immunostaining and negative for CD20 and lysozyme." (PMID 21776287, 2011).
multiple myeloma (5 papers, 2013 to 2025). "These proteins are often immunoglobulin light chains (i.e., Bence Jones proteins), in multiple myeloma but also lysozyme, myoglobin or free hemoglobin can be seen." (PMID 40603713, 2025). "We made use of the Tumor Immune Single-cell Hub (TISCH) database and employed Uniform Manifold Approximation and Projection (UMAP) to examine the expression levels of CKS2 and LYZ in single cells obtained from myeloma tissues." (PMID 37580667, 2023). "These anaplastic myeloma cells are negative for the common leukocyte antigen, lysozyme, and the cytoplasmic immunoglobulins." (PMID 24252328, 2013).
neurosarcoidosis (5 papers, 2022 to 2025). A sarcoidosis that involves the nervous system. "Several studies have shown that CSF sIL-2R has greater diagnostic sensitivity for neurosarcoidosis than ACE or lysozyme, which were normal in our patient." (PMID 40959368, 2025). "In accordance with previous data, we confirm the low sensitivity of serum analysis except for lysozyme levels which were increased in almost 80% of our cohort, while it was reported abnormal in only half of patients with neurosarcoidosis in the literature." (PMID 36388212, 2022). "Additionally, serum ACE and lysozyme levels were within normal limits, further arguing against neurosarcoidosis." (PMID 40688874, 2025). "The value of serum ACE and lysozyme and CSF ACE are limited for diagnosing neurosarcoidosis: sensitivity of serum ACE is 75% in untreated and 35% in treated patients, sensitivity of lysozyme 46% and sensitivity and specificity of CSF ACE is 67% and 67% respectively." (PMID 41328180, 2025). "Negative serum ACE and lysozyme levels also helped exclude alternative inflammatory etiologies, such as neurosarcoidosis." (PMID 40688874, 2025). "However, the measurement of soluble interleukin-2 receptor (sIL-2R) in CSF, although nonspecific, has emerged as a potentially useful biomarker for neurosarcoidosis, particularly in the absence of elevated angiotensin-converting enzyme (ACE) or lysozyme levels." (PMID 40959368, 2025).
ocular sarcoidosis (5 papers, 2016 to 2024). A leading cause of inflammatory eye disease is sarcoidosis. "In ocular sarcoidosis, elevated serum lysozyme has been among the diagnostic criteria indicated by IWOS since 2006 and in the reviewed 2019 IWOS criteria it is even stated as a criterion separate from ACE." (PMID 37721575, 2023). "On the contrary, high serum lysozyme was newly included as a criterion separate from ACE for the diagnosis of ocular sarcoidosis in the revised IWOS diagnostic criteria in 2017." (PMID 33805490, 2021). "Serum lysozyme normal values in children are the same as for adults (9.6–17.1 mg/L), although initially reported in the 80 s to be age dependent in ocular sarcoidosis." (PMID 37721575, 2023). "Another study showed that 61% of patients with ocular sarcoidosis (biopsy-proven or BHL positive) had elevated sACE or lysozyme or both." (PMID 37721575, 2023). "Normal lysozyme values are 9.6–17.1 mg/L for all ages and mean serum lysozyme levels was 39.92 ± 55.5 mg/L in the ocular sarcoidosis group versus 10.5 ± 5.8 mg/L (p ≤ 0.0013) in the control group (n = 30)." (PMID 37721575, 2023). "In ocular sarcoidosis (biopsy-proven or BHL positive or suspected) lysozyme levels were shown to be elevated in 59,4% of patients." (PMID 37721575, 2023). "In ocular sarcoidosis, lysozyme has a sensitivity of 83.7% and a specificity of 90%, which contrasts with sACE’s low specificity." (PMID 37721575, 2023). "The authors of this recent study concluded that lysozyme was found to be more useful than ACE as a laboratory test to support the diagnosis of ocular sarcoidosis." (PMID 37721575, 2023). "In ocular sarcoidosis, lower lysozyme levels were observed in patients with biopsied sub-centimetric mediastinal lymph nodes in comparison to patients that had bigger (≥ 1 cm) lymph nodes." (PMID 37721575, 2023). "On the other hand, serum lysozyme seems more often elevated compared to ACE in our ocular sarcoidosis cases." (PMID 33805490, 2021). "Sensitivity and specificity of polyclonal antibody activation amounted to 70%/90.4% Conclusion: Lysozyme was found to be much more useful than ACE as a laboratory test to support the diagnosis of ocular sarcoidosis." (PMID 33805490, 2021). "Especially in patients with proven ocular sarcoidosis, the mean serum level of lysozyme was higher than in the group of suspected ocular disease." (PMID 33805490, 2021). "Thirty-one of the 37 patients (83%) with proven and/or suspected ocular sarcoidosis were found to have a high level of lysozyme, while this was the case for ACE in only 11 of the 37 patients (29.7%)." (PMID 33805490, 2021). "Mean serum lysozyme levels were 39.92 ± 55.5 mg/L in the ocular sarcoidosis group versus 10.05 ± 5.88 mg/L (p ≤ 0.0013) in the control group (n = 47)." (PMID 33805490, 2021). "Mean serum lysozyme levels was 39.92 ± 55.5 mg/L in the ocular sarcoidosis group versus 10.5 ± 5.8 mg/L (p ≤ 0.0013) in the control group (n = 30)." (PMID 33805490, 2021). "In another study considering the predictive value of serum ACE and lysozyme levels in diagnosis of ocular sarcoidosis, the sensitivity of increased serum ACE level was found as 84 %, specificity was 95 %, and predictivity was 47 %." (PMID 26879979, 2016). "(p = 1.000) Elevated serum lysozyme levels have been included in the criteria for diagnosis of ocular sarcoidosis." (PMID 26879979, 2016). "The serum levels of ACE and lysozyme have been reported increased in 40 and 42 % of patients with biopsy-proven ocular sarcoidosis respectively." (PMID 26879979, 2016). "Lysozyme was found to be much more useful than ACE as a laboratory test to support the diagnosis of ocular sarcoidosis in a study performed by Papasavvas because the number of patients with normal ACE and elevated lysozyme levels were much greater in his study." (PMID 38787250, 2024). "Serum ACE and lysozyme are well documented as ocular sarcoidosis biomarkers." (PMID 37721575, 2023).
ocular sarcoidosis (continued). "Moreover, similarly to systemic sarcoidosis in ocular sarcoidosis there is a correlation between serum lysozyme levels and disease burden." (PMID 37721575, 2023). "However, lysozyme is rarely recommended as a complimentary test for ocular sarcoidosis and is rarely reported in studies." (PMID 33805490, 2021). "Regarding laboratory measurements, serum lysozyme was not determined, which has recently been shown to be a useful diagnostic marker for ocular sarcoidosis." (PMID 35011651, 2021). "In addition, we found that lysozyme was much more sensitive than ACE in the diagnosis of ocular sarcoidosis reaching 83.7% versus 27% for ACE." (PMID 33805490, 2021). "Both studies showed that increased serum lysozyme levels might be less predictive for ocular sarcoidosis." (PMID 26879979, 2016). "Rarely lysozyme can be elevated in ocular infections but it was not elevated in autoimmune ocular disorders other than presumed ocular sarcoidosis." (PMID 37721575, 2023). "There are no studies stating lysozyme sensitivity and specificity in ocular sarcoidosis in children." (PMID 37721575, 2023). "The aim was to evaluate the usefulness of serum ACE, serum lysozyme and polyclonal antibody activation and compare the frequency of increased serum levels of lysozyme and ACE and their sensitivities and specificities in proven ocular sarcoidosis or in suspected ocular sarcoidosis cases." (PMID 33805490, 2021).
acne (4 papers, 2017 to 2024). An inflammatory process of the sebaceous glands which is characterized by comedones, nodules, papules and/or pustules on the skin. "In addition, the use of US contributed to the antibacterial effects of lysozyme-shelled microbubbles on inhibiting the inflammation of acne, but the results of which were limited and lacked the comparisons of other important clinical features associated with acne treatment." (PMID 34095172, 2021). "In the majority of the cases, the MIC of AS-48 plus lysozyme was lower than that of AS-48 alone, confirming previous results protected by a Spanish patent about the effectiveness of AS-48 and lysozyme against acne and other skin bacterial infections." (PMID 30082920, 2018). "In summary, this study supports that compositions comprising the bacteriocin AS-48 plus lysozyme must be considered as promising candidates for topical applications with medical and pharmaceutical purposes against dermatological diseases such as acne vulgaris." (PMID 30082920, 2018). "In contrast, lysozyme cannot kill C. acnes, which may explain its minor upregulation in acne skin biopsies.The expression of AMPs can also be affected by several AV-associated factors, such as FFAs, glucose, insulin, or IGF-1 levels." (PMID 39744637, 2024). "The present study applied lysozyme (LY), an alternative antibiotic, with microbubbles (MBs), and combined them with ultrasound (US) with the aims of reducing the dose and treatment duration and improving the prognosis of acne vulgaris while also avoiding bacterial resistance." (PMID 28117399, 2017).